CENPB (centromere protein B)
Description:
Interacts with centromeric heterochromatin in chromosomes and binds to a specific 17 bp subset of alphoid satellite DNA, called the CENP-B box. May organize arrays of centromere satellite DNA into a higher-order structure which then directs centromere formation and kinetochore assembly in mammalian chromosomes (Probable).
Tractability: Small molecule: a structure with a bound ligand is known. PROTAC: UniProt records ubiquitination sites on it; ubiquitination databases record sites on it; its protein half-life has been measured.
Gene: Protein-coding gene on chromosome 20 (3,783,851 to 3,786,740, reverse strand). Ensembl gene ENSG00000125817.
Subcellular location: Nucleus; Chromosome, centromere
Subcellular location (Human Protein Atlas): Nuclear bodies; Nucleoplasm
Gene Ontology:
Molecular function: protein binding; centromeric DNA binding; chromatin binding; DNA binding; satellite DNA binding; sequence-specific DNA binding; nucleic acid binding
Cellular component: chromosome; chromosome, centromeric region; nuclear body; nucleoplasm; nucleus; condensed chromosome, centromeric region; pericentric heterochromatin
Genetic constraint (gnomAD): Loss-of-function variants: 19 observed, 33.69 expected, observed/expected ratio (o/e) 0.56, 90% interval 0.39 to 0.83. The synonymous counts are far from expectation, so gnomAD's model fits this gene poorly and the ratio says little. Missense variants: 614 observed, 721 expected, observed/expected ratio (o/e) 0.85, 90% interval 0.8 to 0.91. Synonymous variants: 399 observed, 316.35 expected, observed/expected ratio (o/e) 1.26, 90% interval 1.16 to 1.37.
Homologues: Orthologues: chimpanzee CENPB (99% identical), macaque CENPB (97% identical), pig CENPB (95% identical), dog CENPB (94% identical), rat Cenpb (92% identical), mouse Cenpb (92% identical), guinea pig CENPB (83% identical), tropical clawed frog tigd3 (16% identical). Paralogues in human: TIGD4 (24% identical), TIGD6 (22% identical), TIGD5 (21% identical), TIGD3 (21% identical), TIGD2 (20% identical), JRK (19% identical), JRKL (18% identical), TIGD1 (18% identical), TIGD7 (18% identical), POGK (12% identical), POGZ (11% identical).
Diseases named in the same sentence as CENPB in open-access papers:
CENPB is named in the same sentence as 53 diseases in open-access papers, as found by Europe PMC text mining. Sharing a sentence is not in itself a finding about the gene and the disease. The quoted sentences say what the papers report.
systemic sclerosis (13 papers, 2009 to 2025). A chronic disorder, possibly autoimmune, marked by excessive production of collagen which results in hardening and thickening of body tissues. "CENPs, such as CENPA and CENPB, have been discovered to be immune autoantigens of systemic scleroderma." (PMID 36644760, 2022). "Antigens YBX1, HMG-14, and CENPB which showed also informative AUC values are involved in the autoimmune disease systemic sclerosis." (PMID 19284601, 2009).
scleroderma (8 papers, 2011 to 2025). Scleroderma is a rare autoimmune connective tissue disorder characterized by abnormal hardening of the skin and, sometimes, other organs. "ACA is one of the hallmark antibodies in scleroderma, targeting centromere protein-B, an alphoid DNA binding protein." (PMID 31431952, 2018). "Immunoblot tests revealed positive centromere protein B (CENP-B), suggesting a diagnosis of scleroderma." (PMID 39252723, 2024). "EUROLINE Systemic Sclerosis immunoblot has been approved for screening of 13 scleroderma-specific or associated antibodies: anti-Scl-70, CENPA, CENPB, RNAP-III (11 kDa), RNAP-III (155 kDa), fibrillarin (U3-RNP), NOR90, Th/To, PM/Scl-100." (PMID 35454989, 2022). "An extractable nuclear antigen (ENA) profile test revealed a positive centromere protein B (CENP-B) immunoblot result, leading to a conclusive diagnosis of scleroderma." (PMID 39252723, 2024).
autoimmune disease (7 papers, 2009 to 2025). A disorder resulting from loss of function or tissue destruction of an organ or multiple organs, arising from humoral or cellular immune responses of the individual to their own tissue constituents. "CENPB was additionally associated with the autoimmune diseases lupus erythematosus and rheumatoid arthritis." (PMID 19284601, 2009). "The STRING analysis here reveals that CENPB interacts with TRIM21, which is involved in both cancer proliferation and in innate immunity, possibly explaining its role in autoimmune diseases such as systemic lupus erythematosus and in Sjögren’s syndrome." (PMID 34439361, 2021).
breast carcinoma (4 papers, 2012 to 2023). "What is worth noting is that current research has found that antibodies targeting CENPB can prolong the survival of breast cancer patients." (PMID 37925172, 2023). "NPAS4 and CENPB, on the other hand, are both involved with breast cancer." (PMID 28607444, 2017).
systemic lupus erythematosus (3 papers, 2021 to 2026). An autoimmune multi-organ disease typically associated with vasculopathy and autoantibody production. "CENPB interacts also with TRIM21, an E3 ubiquitin ligase, involved in innate immunity, associated to cancer proliferation, as well as in systemic lupus erythematosus and in Sjögren’s syndrome." (PMID 34439361, 2021).
colon cancer (2 papers, 2012 to 2023). "A large-scale parallel sequencing study has found that CENPB protein assists in the formation of kinetochores during mitosis and is involved in the WNT signaling pathway, thereby promoting the progression of colon cancer." (PMID 37925172, 2023).
glioma (2 papers, 2021 to 2025). A benign or malignant brain and spinal cord tumor that arises from glial cells (astrocytes, oligodendrocytes, ependymal cells). "According to Tian W and colleagues, LINC01123 serves as a sponge for miR-151a and upregulates CENPB expression, increasing the radioresistance of glioma cells in vitro and in vivo." (PMID 41149459, 2025). "The survival analysis in brain lower-grade glioma demonstrates a higher survival probability of individuals with medium/low expression level of CENPB than in individuals with high expression levels." (PMID 34439361, 2021). "LINC01123 promotes glioma cell radioresistance by sponging miR-151a and increasing CENPB levels." (PMID 41149459, 2025).
lung fibrosis (2 papers, 2022). "Interestingly, they found that either hypochlorite or hydroxyl radicals can induce systemic disease, cutaneous and lung fibrosis, and anti-topoisomerase I autoantibodies; while those treated with peroxynitrites showed skin fibrosis and anti-centromere protein B antibodies (CENP-B)." (PMID 35629370, 2022).
lung squamous cell carcinoma (2 papers, 2024). "CircTP63, highly expressed in lung squamous cell carcinoma (LUSC) tissues and facilitated cell cycle progression by acting as an miR-873-3p sponge to upregulate the expression of FOXM1, CENPA and CENPB." (PMID 39519039, 2024). "In lung squamous cell carcinoma, circTP63 binds competitively to miR-873-3p and prevents it from suppressing FOXM1, thereby upregulating CENPA and CENPB and promoting cell cycle progression." (PMID 38191906, 2024).
head and neck squamous cell carcinoma (1 paper, 2022). A squamous cell carcinoma that arises from any of the following anatomic sites: lip and oral cavity, nasal cavity, paranasal sinuses, pharynx, larynx, and salivary glands. "For CENPB and CENPBD1, CENPB can be a serum biomarker for the diagnosis of lung cancer, while mRNA expression of CENPBD1 has prognostic value for survival in radio(chemo)therapy-treated head and neck squamous cell carcinoma." (PMID 36421335, 2022).
hepatocellular carcinoma (1 paper, 2023). A malignant tumor that arises from hepatocytes. "Correlation between CENPB protein expression and clinicopathologic features in 490 patients with hepatocellular carcinoma." (PMID 37925172, 2023). "Correlation between CENPB mRNA and clinicopathologic features in 374 patients with hepatocellular carcinoma." (PMID 37925172, 2023). "Hence, the simultaneous targeting of the miR-29a/CENPB axis holds promise as a novel therapeutic strategy for hepatocellular carcinoma." (PMID 37925172, 2023).
liver cirrhosis (1 paper, 2023). "Furthermore, univariate Cox regression analysis identified tumor size, TNM stage, serum AFP levels, liver cirrhosis, and high CENPB protein expression as risk factors influencing OS and RFS." (PMID 37925172, 2023). "As for RFS, liver cirrhosis (P<0.001) and high CENPB protein expression (P=0.002) were identified as independent predictive factors." (PMID 37925172, 2023). "Additionally, the multivariate Cox regression analysis confirmed that serum AFP levels (P=0.049), liver cirrhosis (P<0.001), and high CENPB protein expression (P=0.014) were independent predictors of OS." (PMID 37925172, 2023). "The nomograms for OS and RFS prediction incorporated independent risk factors that were identified through multivariate Cox regression analysis, including tumor diameter, liver cirrhosis, serum AFP levels, and CENPB protein expression." (PMID 37925172, 2023).
neuroblastoma (1 paper, 2014). Neuroblastoma (NB) is the most common solid, extracranial childhood tumor. "A majority of FOXM1 target genes, including CDC25B, CHEK2, CENPA, CENPB, and CENPF, were significantly downregulated in neuroblastoma cells with MEIS2 depletion." (PMID 25210800, 2014).
pancreatic adenocarcinoma (1 paper, 2021). "Indole-3-carbinol affects the expression of 5 different genes (CD47, CENPB, ERGIC1, PPRC1, SLC44A1) that, in turn, affect the survival in patients with uterine corpus endometrial carcinoma (CD47), brain lower-grade glioma (CENPB, ERGIC1) and pancreatic adenocarcinoma (PPRC1, SLC44A1), respectively." (PMID 34439361, 2021).
Raynaud’s syndrome (1 paper, 2021). "CENPB is a gene that encodes a protein that facilitates centromere formation, termed the major centromere autoantigen B, since its antibodies were higher in all patient sera affected by Raynaud’s syndrome." (PMID 34439361, 2021).
rectal cancer (1 paper, 2021). A primary or metastatic malignant neoplasm that affects the rectum. "The CENPB gene is the most interesting in the context of inherited rectal cancer, since it is part of the WNT signaling pathway." (PMID 33827643, 2021). "Further studies are needed to evaluate the involvement of the CENPB and the other genes in inherited rectal cancer." (PMID 33827643, 2021).
cancer (10 papers, 2009 to 2026). A tumor composed of atypical neoplastic, often pleomorphic cells that invade other tissues. "In various types of cancer, CENPB expression is abnormal or dysregulated, and it is associated with tumor progression and poor prognosis." (PMID 37925172, 2023). "This is the first reported cancer syndrome co-segregating with a variant in the CENPB gene." (PMID 33827643, 2021). "The tigger transposable element-derived (TIGD) family proteins appear to be related to the DNA transposons and exhibit homology to centromere protein B (CENP-B), a factor previously associated with various cancers." (PMID 39734333, 2024). "The gene CENPB is down-regulated in Al-10-49 apoptotic treatment, in Withaferin A and Indole-3-Carbinol nutrigenomics treatments, while it is up-regulated in 5 different cancer types." (PMID 34439361, 2021). "Additionally, emerging research suggests that CENPB may be involved in the development of cancer." (PMID 37925172, 2023). "Interestingly, circular RNAs (circRNAs), defined as crucial cancer regulators, decreased the expression of FOXM1 and promoted the expression of CENPA and CENPB to facilitate cell cycle progression." (PMID 36741311, 2023). "Interestingly, investigating on CENPB protein interactors, the results associated not only with other proteins involved in centromere formation, but also with PARP1 which is known to be involved in programmed cell deaths, in cancer, and in the cellular response to DNA damage." (PMID 34439361, 2021).
tumor (3 papers, 2021 to 2023). "Moreover, a univariate Cox regression analysis identified pathologic stage, tumor status, vascular invasion, and CENPB mRNA as influential risk factors impacting both OS and RFS." (PMID 37925172, 2023). "Notably, as the tumor stage and pathological grade advance, there is a gradual increase in CENPB mRNA and protein expression, indicating a strong association between CENPB expression and tumor prognosis." (PMID 37925172, 2023). "Subsequently, a multivariate Cox regression analysis confirmed that tumor status, vascular invasion, and CENPB mRNA all exerted independent effects on OS and RFS." (PMID 37925172, 2023). "Intriguingly, the Kaplan-Meier plotter database’s survival curves demonstrated that even in patients with earlier tumor stages (Stage I+II) and lower pathological grades (Grade 1+2), increased expression of CENPB still correlated with poorer OS and RFS." (PMID 37925172, 2023). "We proceeded to analyze the clinical prognostic significance of CENPB protein expression in patients characterized by low tumor staging, small tumor size, moderate/well differentiation and others." (PMID 37925172, 2023). "Notably, in the TCGA dataset, CENPB mRNA levels exhibited a gradual increase in correlation with tumor stage and pathological grade." (PMID 37925172, 2023). "CENPB may promote tumor development by affecting chromosomal stability and regulating gene expression." (PMID 37925172, 2023). "CENPB plays a multifaceted role in tumorigenesis and tumor progression." (PMID 37925172, 2023). "Notably, CENPB protein showed prognostic value in patients with stage I/II, AFP levels below 400 ng/ml, and tumor size less than 5 cm." (PMID 37925172, 2023).
CENPB also shares sentences with these, for which no sentence is quoted: polymyositis (4 papers); autoimmune hepatitis (2); connective tissue disorder (2); CREST syndrome (2); interstitial lung disease (2); Sjögren’s syndrome (2); adenocarcinoma (1); adenoma (1); Autoimmunity (1); calcinosis (1); Cirrhosis (1); colorectal tumor (1); COVID-19 (1); dermatomyositis (1); endothelial dysfunction (1); glioblastoma (1); Hypertension (1); limited cutaneous systemic sclerosis (1); lung adenocarcinoma (1); lung carcinoma (1); lupus erythematosus (1); lupus nephritis (1); lymphoma (1); mixed connective tissue disease (1); optic neuritis (1); overlap syndrome of (1); portal hypertension (1); pulmonary arterial hypertension (1); renal dysfunction (1); rheumatoid arthritis (1).
A further 5 diseases each share a sentence with CENPB in 1 paper.